VHL (von Hippel-Lindau tumor suppressor)
Diseases named in the same sentence as VHL in open-access papers (continued):
Sharing a sentence is not in itself a finding about the gene and the disease.
tumor (continued). "The activation of those genes with increased expression in the early stages of tumor development is associated with HIF-1-mediated cellular adaptation to the oxygen-deprived microenvironment as well as due to the accumulation of HIF1α caused by the inactivation of the VHL gene." (PMID 34046336, 2021). "Moreover, α-inhibin was detected in VHL case associated with clear cell NET tumor, suggesting that α-inhibin may be a biomarker and an promoter between clear cell NET and VHL." (PMID 34923986, 2021). "Interestingly, in nine patients, the VHL mutations resided in only one of the two tumour samples." (PMID 33946379, 2021). "Thus, the strong Cyclin D1 expression observed in the VHL tumor may be a direct result of the loss of pVHL-dependent transcriptional repression." (PMID 31673890, 2020). "These comprised two truncating pathogenic variants—RB1 R255* and TSC1 R786*, one missense probable damaging variant—VHL tumor suppressor R58W, and four splice variants of unknown significance in ETS2 transcription factor, SGK1 serum/glucocorticoid regulated kinase 1, AXL RTK and MIB1." (PMID 31258848, 2019). "Notably, numerous TSGs were also reported to be hypermethylated in RCC samples compared to normal tissue (APAF-1, APC, BTG3, CDH1, Gamma-catenin, GATA-3, HOX-B-13, KILLIN, RARβ2, RASSF1A, TIMP3, VHL, and others), associating with increased tumor cell proliferation, invasion, and metastization." (PMID 29706891, 2018). "However, to determine whether bexarotene could affect tumor growth in VHL-deficient cells by modulating AURKA, we established an RCC tumor xenograft using 786-0 (VHL-deficient) cells in athymic nude mice (Foxn1nu)." (PMID 30518623, 2018). "In addition to this, 104 single cells classified as CRC-UMF by morphological examination were also found to carry the same VHL mutation detected in the corresponding tumorous tissue and could be considered as tumor cells." (PMID 29732003, 2018). "This difference could be a reflection of molecular mechanisms responsible for CA IX expression: high CA IX expression in other tumours than ccRCC is hypoxia-related, whereas, is linked to VHL inactivation in ccRCC, where the latter is itself a marker of good prognosis." (PMID 29251173, 2018). "PGLs may also associate with germline mutations in the von Hippel-Lindau (VHL) tumor suppressor." (PMID 28036268, 2017). "Moreover, lipid deposition in ccRCC cells depends on loss of the VHL tumor suppressor." (PMID 29176561, 2017). "Whereas iron accumulation in VHL-deficient ccRCC tumor cells might increase HIF-2α through IRP1 deactivation and in turn promote TFRC transcription, iron accumulation in VHL wild-type tissues would be expected to decrease HIF-2α through PHD activation and lead to TFRC downregulation." (PMID 29291011, 2017). "Thus, partial loss of function of VHL in endothelium may be a contributing factor in tumor angiogenesis through a VEGF-independent mechanism." (PMID 28710479, 2017). "Loss of heterozygosity (LOH) found in VHL‐related tumor samples verifies the hypothesis." (PMID 28776935, 2017). "Interestingly, in the metachronous bilateral ccRCC patient BC_3, four regions in the right tumor harbored the same VHL mutation, while a different VHL mutation was present in the left tumor, suggesting that different regions in the right tumor had a common origin and the left tumor was independent." (PMID 27383411, 2016).
tumor (continued). "Previous work indicates that VHL loss may promote a more aggressive and metastatic tumour model." (PMID 27358011, 2016). "By extension, it is feasible that the type of VHL mutation could affect tumour development." (PMID 27174753, 2016). "In particular, a VHL D121G mutation was found in both samples with high allele frequencies (~1.0), suggesting that it might be a founder event in tumor evolution." (PMID 27139883, 2016). "Pseudo-hypoxia may be achieved through inactivation of tumor-suppressor genes, such as the von Hippel–Lindau (VHL) tumor suppressor, E3 ubiquitin ligase gene (VHL); the genes associated with the succinate dehydrogenase (SDH) complex (the SDHx genes); and the fumarate hydratase (FH) gene." (PMID 27047799, 2016). "Simply, the abundance of minute structural changes in VHL tissues is explained more easily by an origin from VHL-deficient aberrant cells; furthermore, the most frequent occurrence of precursor structures in nerve root tissue provides a very limited set of candidate cells for tumor development." (PMID 28326266, 2015). "Thus, VHL gene mutations significantly increase the risk of tumor growth in target organs." (PMID 24959293, 2014). "Therefore, it is anticipated that loss of VHL function might bring about different phenotypes based upon the molecular composition of tumor cells and upon other cellular signals that can foster Snail expression." (PMID 25025131, 2014). "Unfortunately the VHL mutation status of these tumours is in most cases unknown." (PMID 23606570, 2013). "Several chromosomal regions are frequently amplified or deleted and numerous genes are frequently hypermethylated in ccRCC, implying that there may be many different combinations of genetic alterations that can cooperate with loss of VHL function to cause tumour formation." (PMID 23606570, 2013). "We chose this approach to avoid identifying differentially expressed proteins in direct comparisons of SDHB and VHL-PHEOs/PGLs that may be due to tumor location, the different mutations, or other factors that are not necessarily related to the aggressive behavior of SDHB tumors." (PMID 22859959, 2012). "Therefore, LINE-1 methylation levels were evaluated among heterogeneous case subgroups to examine whether risk of having a specific type of VHL alteration in tumor DNA might be modified by global methylation levels in genomic DNA." (PMID 22076155, 2011). "Therefore, loss of VHL in these tumours leads to persistently elevated levels of HIF expression." (PMID 20492653, 2010). "Although the precise molecular mechanism of regulated CAIX shedding remains to be clarified, previous studies showed that dysregulation of HIF-1α could be caused by mutation in the von Hippel-Lindau (VHL) tumour suppressor gene or activation of the epidermal growth factor receptor (EGFR)." (PMID 20461082, 2010). "Disparities among the pVHL mutants in their ability to ubiquitinate HIF-α (through deficiencies either in HIF-α binding or in ability to form a functional E3 ligase complex) have been suggested to underlie the differences in tumor risks among the VHL disease subtypes." (PMID 19602254, 2009). "For these experiments, we utilized paired mutations with alternate amino acids at the same VHL codon that result in different VHL disease subtypes, based on the notion that they may reveal differences in VHL biochemical functions that are relevant to differential tumor risk." (PMID 19602254, 2009). "Since somatic VHL mutations account for the majority of sporadic CCRCCs and may represent a prognostic factor we sought for mutations of the VHL gene in different samples of tumor DNA including frozen cDNA obtained from the cells left inside the needle used for fine-needle aspiration cytology." (PMID 17067398, 2006). "However, the tumor size was larger for VHL mutated clear-cell RCC." (PMID 15932632, 2005).
tumor (continued). "Detailed analysis of the regions of LOH on chromosome 3p suggested that, in addition to the VHL gene in chromosome 3p25-p26, mutations in one or more tumour-suppressor genes in chromosome 3p13-p24 may be involved in the pathogenesis of sporadic renal cell carcinoma (RCC)." (PMID 8297719, 1994). "By analyzing the metabolomics data from plasma and tumor tissues alongside subsequent expression validation, we identified L-Asparagine (L-Asn) as the differential metabolite in VHL-mutant RCC, with its levels significantly decreased in these tumors." (PMID 41943831, 2026). "Transcriptomic profiling and an RNA interference-based rescue screen identified KCNK3, a putative tumor suppressor, as a key mediator of DNMT inhibitor-induced synthetic lethality in VHL-deficient RCC." (PMID 41792232, 2026). "Hypoxia-induced lncRNAs can improve tumor cell sensitivity to hypoxia signaling pathways by attaching to the HIF inhibitory protein VHL and blocking HIF degradation." (PMID 41614928, 2026). "First, we employed untargeted metabolomics and ELISA to identify and confirm the differential metabolite in the plasma and tumor tissues of VHL-mutant RCC patients." (PMID 41943831, 2026). "Both SKPin C1 and vinorelbine significantly inhibited the tumor growth of 786-O VHL-/- xenografts in nude mice." (PMID 40384876, 2025). "The von Hippel-Lindau (VHL) tumor suppressor is a substrate-defining component of E3 ubiquitin ligase complexes that target cellular substrates for proteasome-mediated degradation." (PMID 40240354, 2025). "In the scenario where CCRCC serves as the recipient tumor, due to the inactivation of the von Hippel-Lindau (VHL) gene in CCRCC, hypoxia-inducible factor (HIF) is overexpressed abnormally." (PMID 41476587, 2025). "Loss of VHL function activates hypoxia-inducible factor (HIF) signaling by stabilizing HIF-α proteins, thereby promoting tumor angiogenesis, metabolic reprogramming, and ammonia accumulation." (PMID 40821775, 2025). "The von Hippel-Lindau (VHL) E3 ubiquitin ligase has seen extensive research due to its involvement in the ubiquitin proteasome system and role as a tumor suppressor within the hypoxia signaling pathway." (PMID 39834300, 2025). "The VHL gene is the major tumor suppressor in ccRCC pathogenesis and a conductor of oxidative-glycolytic glucose metabolism." (PMID 41301058, 2025). "VH032, a novel ligand for VHL, has a unique mechanism of action that opens new avenues for tumor therapy." (PMID 41030787, 2025). "RCC is a vascular-rich tumor, mainly due to inactivation of the mutant gene VHL, leading to an abnormal accumulation of HIF-1/2α and initiating an angiogenic program with elevated levels of VEGF." (PMID 41405787, 2025). "Patient demographics, VHL status, and tumor characteristics have been analyzed to identify factors potentially impacting treatment outcomes." (PMID 40091097, 2025). "We confirm a significant association of VHL mutation and chromosome 3p deletion frequency with EUR genetic similarity, and we also identify distinct gene expression patterns and tumor microenvironment compositions associated with AFR and EUR groups." (PMID 40131247, 2025). "The pooled prevalence of RCC in VHL patients was 45% (95% CI: 40–50%), with a mean tumor size of 3.5 cm (SD: 1.2 cm)." (PMID 40937003, 2025). "Genetic studies, next-generation sequencing data and transgenic mouse models illustrate the central role of the von Hippel–Lindau (VHL) tumor suppressor and the downstream hypoxia pathway in ccRCC pathogenesis." (PMID 41301058, 2025). "In cancer, tumor suppressors that block the function of these signaling pathways, like liver kinase B1, phosphatase and tensin homolog (PTEN), and VHL, are frequently epigenetically silenced, which causes their metabolic reprogramming." (PMID 40581650, 2025).
tumor (continued). "Further characterization of the mechanisms of SKIDA1’s tumor suppressive function in ccRCC and expanded characterization of other VHL-pRb regulated transcriptional targets in ccRCC is needed to appreciate the scope and mechanism of pRb dysregulation in ccRCC." (PMID 40240354, 2025). "Considering that a key marker of ccRCC is the inactivating mutation of VHL, leading to the accumulation of HIF-1/2α and reprogramming of tumor metabolism, we examined the effect of DMF on HIF-1/2α." (PMID 40461489, 2025). "Patient #6 showed low FABP5 expression level in the tumor; later we found that its VHL was wild type, which suggested that FABP5 expression is possibly related with HIF pathway." (PMID 40391655, 2025). "Functionally, ERCC6L promoted LUAD cell stem-like characteristics by regulating tumor glycolysis via the VHL/HIF-1α pathways." (PMID 40691138, 2025). "The idea to check FSHR1 expression in VHL-associated tumors originated during our earlier work, where we first described the ectopic expression of FSHR1 on the endothelial cells of tumor BV." (PMID 41024941, 2025). "Functional validation of key SRGs, including L3MBTL2 and VHL, confirmed their tumor-suppressive roles." (PMID 40821814, 2025). "While VHL dysfunction promotes aggressive tumor phenotypes, the therapeutic potential of VHL restoration remains underexplored." (PMID 41226668, 2025). "Downregulation of HIF2α was shown to be sufficient to suppress tumorigenesis in VHL-defective ccRCC cells, while stable expression of VHL-resistant HIF2α can promote tumor growth in ccRCC cells reconstituted with VHL." (PMID 40240354, 2025). "This agent targets HIF transcription by impairing its heterodimerization with HIF-1b (ARNT), leading to durable disease control across various VHL-related neoplasms." (PMID 40937004, 2025). "The VHL gene produces two proteins that exist in cells and are capable of tumor suppression, VHLp30, which is translated from the first start codon, and VHLp19, which is translated internally from the second start codon." (PMID 39883230, 2025). "Cluster 1A tumours commonly exhibit PVs in the Krebs cycle and SDHx genes, while Cluster 1B tumours involve PVs in the hypoxia-signalling and von Hippel-Lindau pathways (VHL)." (PMID 41141222, 2025). "Taken together, these results showed several changes related to tumor progression and immunomodulatory pathways in ccRCC upon VHL restoration." (PMID 40736709, 2025). "The loss of VHL function can lead to increased HIF stabilization and upregulation of pro-tumorigenic factors, such as VEGF, thereby promoting tumor growth and metastasis." (PMID 40005423, 2025). "The Clinical Proteomic Tumor Analysis Consortium (CPTAC) found that VHL expression levels were lower in ccRCC tumor tissues than in normal tissues." (PMID 39781455, 2025). "PBRM1 truncating mutations are found in up to 41% of cases, making it the second most commonly mutated gene after VHL, while BAP1 and SETD2 mutations are associated with aggressive histological features, higher tumor grades, and poorer survival outcomes." (PMID 40361369, 2025). "By leveraging the attention weights and prediction scores generated by the ABMIL model, attention heat maps demonstrated the model’s focus on tumor regions for high-TMB patients, reflecting a marked stromal lymphocytic infiltration for VHL mutation prediction." (PMID 40217721, 2025). "Multivariable binary logistic regression analysis of increased MIB-1 index (≥ 3%) considering EoR and tumor origin (VHL/sporadic) was performed." (PMID 41382243, 2025). "Consistent with this knowledge, biallelic inactivation of the VHL tumor-suppressor gene is also the initiating event in most sporadic ccRCCs." (PMID 40178040, 2025). "Dividing the tumors into those that express the wild-type VHL gene and those with the mutated VHL gene, the quantification of HIF1A revealed decreased expression in both tumor types compared to the surrounding healthy tissue." (PMID 40332447, 2025).
tumor (continued). "This early event contributes to the two-hit inactivation of key tumor-suppressive loci, particularly VHL, thereby initiating the molecular cascade that drives ccRCC development." (PMID 41584840, 2025). "The von Hippel–Lindau (VHL) tumor suppressor (pVHL) protein is a tumor suppressor that promotes the degradation of hypoxia-inducible factor-α (HIF-α)." (PMID 41050073, 2025). "In fact, ANGPTL4 exhibited a tumor suppressive effect in VHL WT tumors by inhibiting lysosomal acid lipase." (PMID 40233044, 2025). "When a tumor is suspected to be sporadic, the INT2GRATE|VEF requires additional steps to assess somatic VHL alleles." (PMID 40647474, 2025). "The majority of ccRCC cases are characterized by VHL gene inactivation, leading to persistent HIF2α activation, which drives the expression of angiogenic factors and promotes tumour angiogenesis." (PMID 40435846, 2025). "Recent studies have demonstrated that upregulating HIF-1α in CD8+ T cells through VHL knockdown enhances cytotoxic function and suppresses tumor growth." (PMID 40343532, 2025). "Further, tumor proteomes reflected canonical VHL-driven metabolic reprogramming, including upregulated glycolysis and hypoxia markers, suppressed aerobic metabolism, and dysregulated fatty acid metabolism." (PMID 40753869, 2025). "Earlier studies in VHL syndrome have shown that belzutifan can induce tumor regressions across various VHL-associated lesions, with an ORR nearing 90% in indolent VHL-related pNETs." (PMID 41300999, 2025). "The VHL tumor suppressor gene, located on chromosome 3p, plays a central role in the pathogenesis of ccRCC." (PMID 40677703, 2025). "VHL is a tumor suppressor and E3 ubiquitin ligase that degrades hypoxia-inducible factor (HIF) under normoxic conditions." (PMID 40736709, 2025). "We analyzed tumor and healthy tissues from 43 ccRCC patients after radical nephrectomy and cultured 786-O (biallelic VHL inactivation) and Caki-1 (wild-type VHL) cells in normal (21% O2) and low oxygen (3% O2) with 10% and 2% fetal bovine serum (FBS)." (PMID 40332447, 2025). "Suggests that one possible treatment approach for ccRCC is to target the VHL-PDGFRβ-lactylation axis, especially by breaking the feedback loop that encourages tumor development." (PMID 39968078, 2025). "In 10 of these 29 patients, somatic mutations were detected: six tumours with a somatic mutation in the NF1-gene, and two patients each with mutations in the EPAS1- and the VHL-gene." (PMID 41276740, 2025). "Upon inhibition of HIF2α, a greater infiltration was observed in VHL mutant 786-O RCC tumor spheroids." (PMID 40736709, 2025). "•It exerts potent antitumor effects by inhibiting tumor cell proliferation, migration, and invasion through suppression of the VHL/HIF-1α/VEGF signaling pathway, while also inducing apoptosis and G2/M phase cell cycle arrest." (PMID 41030787, 2025). "Orthotopically xenografted (VHL-mutant ccRCC 786-O human cells) mice underwent a 13C 6-glucose infusion for 60 minutes prior to matched tissue sampling (tumour and kidney)." (PMID 41213938, 2025). "Yang reported that lincRNA-p21 interacts with HIF1α, disrupting HIF1α/VHL axis and leading to accumulating of HIF1α, which subsequently promotes glycolysis and tumor growth under hypoxia condition." (PMID 41361062, 2025). "UBE2M has been found to mediate the neddylation of TRIM21 and promote ubiquitination degradation of Von Hippel-Lindau (VHL) tumor suppressor by increasing TRIM21 and VHL interactions." (PMID 40735642, 2025). "Given this established link between VHL status and tumor aggressiveness, we now utilize single-cell RNA sequencing to deconvolve the cellular heterogeneity within this model." (PMID 41226668, 2025). "The von Hippel-Lindau (VHL) protein (pVHL) functions as a potent tumor suppressor by mediating the degradation or inactivation of various substrates, including HIFα and Akt." (PMID 41015595, 2025).